ENSG00000276179
Gene: Miscellaneous RNA gene on chromosome 11 (84,890,744 to 84,890,961, forward strand). Ensembl gene ENSG00000276179.
Gene Ontology:
Biological process: regulation of gene expression